ZMPSTE24 (zinc metallopeptidase STE24)
Diseases named in the same sentence as ZMPSTE24 in open-access papers (continued):
Sharing a sentence is not in itself a finding about the gene and the disease.
dilated cardiomyopathy (2 papers, 2014 to 2023). Cardiomyopathy which is characterized by dilation and contractile dysfunction of the left and right ventricles. "Supporting this assumption, the observation of impaired autophagy in our model is similar to those obtained in some LMNA-related murine models: such as Lmna knockout mice (dilated cardiomyopathy and muscle dystrophy) and Zmpste24-deficient mice (extreme phenotype of premature aging)." (PMID 24753226, 2014).
dysplasia (2 papers, 2016 to 2022). A usually neoplastic transformation of the cell, associated with altered architectural tissue patterns. "Molecular genetic diagnosis allowed the identification of a new homozygous mutation in the ZMPSTE24/FACE1 gene’s exon 10: c.1274T > C, p.(Leu425Pro), confirming the B-type Mandibuloacral dysplasia phenotype in the patient." (PMID 27409638, 2016).
Emery-Dreifuss muscular dystrophy (2 papers, 2013 to 2025). Emery-Dreifuss muscular dystrophy (EDMD) is characterized by muscular weakness and atrophy, with early joint contractures and cardiomyopathy. "Mice lacking Lmna surfer from growth retardation and muscle dystrophy, resembling Emery-Dreifuss muscular dystrophy (EDMD); depleting Zmpste24 in mice recapitulates many progeroid features found in HGPS patients." (PMID 24764515, 2013).
generalized lipodystrophy (2 papers, 2014 to 2019). Almost complete absence of subcutaneous and/or visceral adipose tissue. "MAD patients characterized by generalized lipodystrophy (type B) affecting the face as well as extremities and severe progressive glomerulopathy present heterozygous compound mutations in the ZMPSTE24 gene." (PMID 25286833, 2014).
lung fibrosis (2 papers, 2018 to 2021). "We recently examined the transcriptomic profile of the lungs of young and old normal and Zmpste24 deficient mice after bleomycin-induced lung fibrosis to explore some of the fibrotic mechanisms associated with accelerated aging." (PMID 33982668, 2021). "To better understand the mechanisms by which old Zmpste24 deficient mice are protected from bleomycin-induced lung fibrosis, we examined the transcriptome expression profiling of the aged mice." (PMID 30530916, 2018). "In a previous study, performed to clarify the role of aging in the development of lung fibrosis in Zmpste24 deficient mice that represent an accelerated aging-model, we evaluated by RNA microarray analysis differentially expressed genes in old compared to young WT mice lungs." (PMID 33982668, 2021). "To clarify the role of aging in the development of lung fibrosis and unveiling whether Zmpste24 deficient mice could be an appropriate aging-model for this purpose, we examined their fibrotic response to bleomycin-induced lung damage." (PMID 30530916, 2018). "In order to investigate possible mechanisms that may explain the resistance of the accelerated aged Zmpste24 deficient mice to bleomycin-induced lung fibrosis, we compared the lung transcriptome signature of the injured old Zmpste24 deficient mice with those of old WT mice." (PMID 30530916, 2018). "Unexpectedly, while old WT mice developed severe lung fibrosis, accelerated aged Zmpste24-/- mice were protected showing scant lung damage." (PMID 30530916, 2018). "Unexpectedly, we found that old but not young Zmpste24 deficient mice seem to be protected to the development of bleomycin-induced lung fibrosis finding that was related to an upregulation of the microRNAs miR23a, miR27a, miR29a, and miR145a." (PMID 30530916, 2018). "miR27-a, another upregulated miRNA in bleomycin-injured Zmpste24 deficient mice, functions via negative-feedback mechanisms decreasing lung myofibroblast differentiation, and therapeutically mitigates bleomycin-induced lung fibrosis in mice." (PMID 30530916, 2018). "Taking together, these results suggest that both aging and the absence of Zmpste24 protect mice for developing pulmonary fibrosis." (PMID 30530916, 2018).
metabolic syndrome (2 papers, 2016 to 2017). A cluster of metabolic risk factors for CARDIOVASCULAR DISEASES and TYPE 2 DIABETES MELLITUS. "In a separate study of 87 ‘typical’ metabolic syndrome patients, 10 patients had perturbed lamin A/C distribution and nuclear shape defects: among these, two patients had a LMNA variant (p.G411D or p.G631D), and a third patient had a ZMPSTE24 mutation and accumulated farnesylated prelamin A." (PMID 28663758, 2017).
sarcopenia (2 papers, 2023 to 2024). Progressive decline in muscle mass due to aging which results in decreased functional capacity of muscles. "Together, these results demonstrate the age-related neuromuscular tissue deficiencies in progeroid ZMPSTE24-deficient mice are comparable to those of sarcopenia." (PMID 37535205, 2024). "As observed in other aging models, the skeletal muscle of ZMPSTE24-deficient mice undergoes muscle degeneration with characteristics similar to human sarcopenia." (PMID 37535205, 2024).
arterial disease (1 paper, 2024). "In cultured cells, progerin and full-length farnesyl-prelamin A (produced in Zmpste24−/− cells) form an abnormal nuclear lamin meshwork accompanied by nuclear membrane ruptures and cell death; however, these proteins differ in their capacity to cause arterial disease." (PMID 39554077, 2024).
Arthritis (1 paper, 2025). Inflammation of a joint. "Immunohistochemical staining of Zmpste24 demonstrated a significant decrease in its expression in surgical and natural ageing arthritis models by 50%." (PMID 40461512, 2025). "In conclusion, the expression of Zmpste24 decreases in inflammatory and aging microenvironments, indicating its involvement in arthritis and ageing." (PMID 40461512, 2025).
central obesity (1 paper, 2016). "Here we report detailed clinical phenotype and cellular investigations for a patient carrying a heterozygous missense mutation in ZMPSTE24 and referred for common central obesity with metabolic syndrome (MS)." (PMID 27120622, 2016).
Failure to thrive (1 paper, 2023). Failure to thrive (FTT) refers to a child whose physical growth is substantially below the norm. "In contrast, the homozygous LmnaL648R/L648R mice develop failure to thrive and bone defects that are similar to, albeit less severe and of later onset, than those in Zmpste24−/− mice." (PMID 37885131, 2023).
heart failure (1 paper, 2020). Inability of the heart to pump blood at an adequate rate to meet tissue metabolic requirements. "In this retrospective, cross-sectional study we analyzed blood samples from 110 heart failure patients for quantitative mRNA expression of ZMPSTE24, lamin A/C, progerin and hs-CRP protein." (PMID 32872320, 2020).
Hepatic steatosis (1 paper, 2018). Steatosis is a term used to denote lipid accumulation within hepatocytes. "In addition, mutations in LMNA and ZMPSTE24 in patients lead to metabolic dysfunction, including type 2 diabetes and hepatic steatosis." (PMID 29484800, 2018). "Hepatic steatosis is a common phenotype for aged mice, Zmpste24 mutants, and liver‐specific Lmna knockouts." (PMID 29484800, 2018). "Hence, additional Foxa2 binding in Zmpste24 mutants, like in old liver, leads to activation of gene expression that contributes to hepatic steatosis." (PMID 29484800, 2018). "We observe striking similarities between old and Zmpste24 mutant livers, including nuclear abnormalities, changes in lamin A expression, and increased Foxa2 binding leading to de‐repression of PPAR‐ and LXR‐dependent gene expression that contributes to development of fatty liver." (PMID 29484800, 2018).
Huntington disease (1 paper, 2025). Huntington disease (HD) is a rare neurodegenerative disorder of the central nervous system characterized by unwanted choreatic movements, behavioral and psychiatric disturbances and dementia. "Notably, BMs appeared in chronologically young mice with progeroid or disease-driven aging, including in 4-month-old Zmpste24−/− (lifespan ∼5 months) and 3-month-old Huntington’s disease model mice (lifespan ∼4 months)." (PMID 40347138, 2025).
ichthyosis prematurity syndrome (1 paper, 2012). Ichthyosis prematurity syndrome is a rare, syndromic congenital ichthyosis characterized by premature birth (at gestational weeks 30-32, in general) in addition to thick, caseous and desquamating epidermis, neonatal respiratory asphyxia, and persistent eosinophilia. "Restrictive dermopathy in humans has now been linked to mutations in the zinc metalloproteinase ZMPSTE24 whereas mutations in Fatp4 in humans cause ichthyosis prematurity syndrome (IPS)." (PMID 23226340, 2012).
lumbar disc herniation (1 paper, 2026). "Zmpste24 KO mice exhibited a more severe IVDD phenotype, suggesting the importance of Zmpste24 in lumbar disc herniation." (PMID 41522494, 2026).
mandibuloacral dysplasia with type B lipodystrophy (1 paper, 2018). "Moreover, alterations of the lamin A maturation process also give rise to premature aging features as attested by the restrictive dermopathy (RD) and the mandibuloacral dysplasia with type B lipodystrophy (MADB), which arise from mutations in the ZMPSTE24 gene." (PMID 30545089, 2018).
melanoma (1 paper, 2025). A malignant, usually aggressive tumor composed of atypical, neoplastic melanocytes. "Notably, two serine proteases—plasminogen (Plg) and the CAAX prenyl protease 1 homolog (Zmpste24)—were detected only in melanoma, while two metabolic serine hydrolases—phospholipase B-like 1 (Plbd1) and carboxylesterase 1F (Ces1f)—were found only in normal skin." (PMID 39934865, 2025).
Micrognathia (1 paper, 2020). Developmental hypoplasia of the mandible. "Atypical HGPS and MAD‐B patients exhibit several clinical phenotypes including stunted growth, lipodystrophy, micrognathia, and hair loss, which overlap substantially, albeit not completely, with those of Zmpste24‐deficient mice." (PMID 32910507, 2020).
neurodevelopmental disabilities (1 paper, 2019). "The ZMPSTE24 gene mutated in MADB patients encodes the zinc metalloprotease enzyme involved in production of mature lamin A. We therefore hypothesize that downregulation of LMNA transcripts in the brain might also explain the lack of neurodevelopmental disabilities in MADB patients." (PMID 31856865, 2019).
pancreatic cancer (1 paper, 2014). "The upstream sequence of exon 5 of RLF gene (ENST00000372771) was acquired in pancreatic cancer cell line PA043, and was found to be a sequence from exon 2 to part of exon 5 of ZMPSTE24 gene (ENST00000372759)." (PMID 24533689, 2014).
progeria-like syndromes (1 paper, 2016). "Up to now, pathological phenotypes related to mutations in ZMPSTE24 were linked to homozygous or compound heterozygous mutations and resulted in RD, MAD, or progeria-like syndromes." (PMID 27120622, 2016).
SARS-CoV-2 (1 paper, 2022). "Overexpression of ZMPSTE24 protects against SARS-CoV-2 pseudovirus infection." (PMID 36197088, 2022).
steatosis (1 paper, 2018). Increased lipid within the cytoplasm of cells. "Analogous pathways are affected by Foxa2 binding in Zmpste24‐deficient livers as in older hepatocytes, including activation of genes regulated by PPARα and LXR, factors that contribute to steatosis in older livers." (PMID 29484800, 2018).
cancer (8 papers, 2014 to 2024). A tumor composed of atypical neoplastic, often pleomorphic cells that invade other tissues. "Loss of ZMPSTE24 accelerates senescence associated with cancer." (PMID 35168607, 2022). "Zmpste24 mosaic mice that contain both Zmpste24-proficient cells and Zmpste24−/− cells have revealed a lower incidence of invasive carcinomas compared to mice that are heterozygous for Zmpste24." (PMID 27482812, 2016). "A recent study showed that silencing of ZMPSTE24 reduces cancer cell invasion, suggesting that it could potentially serve as a new therapeutic target." (PMID 26214687, 2015). "Functional change of ZMPSTE24 may induce DNA damage and lead to cancer." (PMID 24533689, 2014).
genetic disorder (3 papers, 2023 to 2025). "Alterations in lamin A, particularly those associated with disruptions in posttranslational processing of lamin A by zinc metallopeptidase ste24, have been linked to a variety of genetic disorders that give rise to genome instability and accelerated aging." (PMID 41352127, 2025). "The deficiency of ZMPSTE24 could induce Hutchinson–Gilford progeria syndrome (HGPS), a genetic disorder of rapid aging." (PMID 37217512, 2023).
infection (2 papers, 2022). The state of being infected such as from the introduction of a foreign agent such as serum, vaccine, antigenic substance or organism. "We note that the susceptibility of ZMPSTE24 KO cells to infection may actually be underestimated here due to the lower ACE2-mCherry levels in these cells compared to WT cells." (PMID 36197088, 2022). "Thus, in agreement with previous findings, ZMPSTE24 deficiency sensitizes cells to infection by VSV-G-pseudotyped lentivirus." (PMID 36197088, 2022). "Furthermore, knockout mutations of ZMPSTE24 (or small interfering RNA [siRNA] knockdown) in cells and mice caused them to succumb to infection by influenza A virus (IAV) and other viruses." (PMID 36197088, 2022). "Here, we show that overexpression of ZMPSTE24 reduces the efficiency of cellular infection by SARS-CoV-2 Spike-pseudotyped lentivirus and that genetic knockout or small interfering RNA-mediated knockdown of endogenous ZMPSTE24 enhances infectivity." (PMID 36197088, 2022). "While the mechanistic relationship between IFITMs and ZMPSTE24 remains to be clearly defined, these findings place ZMPSTE24 at an important position in the cell’s first line of innate defense against infection by many viruses." (PMID 36197088, 2022). "As anticipated, ZMPSTE24 knockout increased LCMVpp and LASVpp infection but this was abrogated in the presence of ZMPSTE24-FLAG." (PMID 35283811, 2022). "Using complementary arenavirus GP-pseudoparticle (GPpp) and live MOPV infection assays, we demonstrated that ZMPSTE24 restricts the entry and replication of arenaviruses." (PMID 35283811, 2022). "For both cell types, ZMPSTE24 KO cells show a substantially greater level of infection than WT cells by fluorescence microscopy." (PMID 36197088, 2022). "WT and Zmpste24−/− mouse embryonic fibroblasts (MEFs) were infected with MHV at a multiplicities of infection (MOIs) of 1 and 10, and cell viability and plaque assays were performed." (PMID 36197088, 2022). "We observed that AmphoB produced a broadly significant reversal of ZMPSTE24-mediated restriction of arenavirus GPpp infection, rendering these cells less sensitive to ZMPSTE24 inhibition." (PMID 35283811, 2022). "Specifically, cells in which ZMPSTE24 is knocked out or its expression knocked down are sensitized to infection by SARS-CoV-2-pseudotyped lentivirus, compared to WT cells." (PMID 36197088, 2022). "Quantitation of the luciferase signal confirmed these higher levels of infection in ZMPSTE24 KO versus WT cells, which were ~3-fold higher for HeLa cells and ≥2-fold higher for HEK293T cells." (PMID 36197088, 2022). "Pre-treatment with AmphoB rescued the entry and fusion of arenavirus GPpp and live MOPV infection in cells expressing either ZMPSTE24 alone or co-expressing ZMPSTE24 and IFITM3." (PMID 35283811, 2022). "For the MLV pseudoparticles, entry occurs by macropinocytosis and we observed little effect of ZMPSTE24 expression on MLV infection." (PMID 35283811, 2022). "Knockdown (KD) of ZMPSTE24 expression with siRNA resulted in increased infection by SARS-CoV-2 Spike-pseudotyped lentivirus compared to treatment with a control (scrambled) siRNA, as detected by immunofluorescence and measured by the luciferase assay." (PMID 36197088, 2022). "To determine if ZMPSTE24 protects cells from a live coronavirus infection, we examined infection of mouse cells by MHV, a murine betacoronavirus distantly related to SARS-CoV-2 but that is amenable to testing at a biosafety level 2 (BSL-2) laboratory." (PMID 36197088, 2022). "Here, we determined that ZMPSTE24 defends cells from infection mediated by SARS-CoV-2 Spike protein using pseudovirus and cell-cell fusion assays." (PMID 36197088, 2022). "We generated SARS-CoV-2 Spike-pseudotyped lentivirus carrying ZsGreen and luciferase reporters to determine if ZMPSTE24 depletion influenced infection of HEK293T cells that had been stably transduced with ACE2 (or ACE2-mCherry), which encodes the SARS-CoV-2 receptor." (PMID 36197088, 2022).
infection (continued). "Depletion of ZMPSTE24 enhances infection by SARS-CoV-2 Spike-pseudotyped lentivirus." (PMID 36197088, 2022). "Furthermore, the ZMPSTE24-E336A catalytically dead mutant inhibited infection roughly to the same extent as WT ZMPSTE24, in agreement with previous findings with other viruses and pseudoviruses." (PMID 36197088, 2022). "Dorf’s group showed that, like the IFITMs with which it interacts, overexpression of ZMPSTE24 robustly protects cells from infection by many pathogenic enveloped viruses, but not all (e.g., murine leukemia virus [MLV] is an exception), and that its proteolytic activity is not needed in this role." (PMID 36197088, 2022). "Depletion of ZMPSTE24 in these cells resulted in significantly higher levels of MOPV genome and infectious virus production throughout the course of infection." (PMID 35283811, 2022). "Upon stable overexpression by retroviral transduction of ZMPSTE24-FLAG, in these ZMPSTE24 KO cells, we observed a marked decrease in LCMVpp, LASVpp, and MOPVpp infection, but not that of MLVpp." (PMID 35283811, 2022). "Furthermore, we found that protection from infection by SARS-CoV-2 Spike-pseudotyped virus and diminished Spike-AceIIACE2-mediated cell-to-cell fusion were promoted equally as well as by WT and catalytically dead forms of ZMPSTE24." (PMID 36197088, 2022). "Likewise, comparing infection of ZMPSTE24 KO and WT cells, the lack of ZMPSTE24 in KO cells increased infection, based on the luciferase assay." (PMID 36197088, 2022). "Overexpression of ZMPSTE24 in NT control cells abrogated LCMVpp and LASVpp infection but in the absence of IFITM expression, the sensitivity of arenavirus entry to ZMPSTE24 restriction was decreased." (PMID 35283811, 2022).
ZMPSTE24 also shares sentences with these, for which no sentence is quoted: muscular dystrophy (3 papers); age (2); alopecia (2); familial partial lipodystrophy (2); hypophosphatasia (2); acquired lipodystrophy (1); AIDS (1); Arrhythmia (1); CANDLE syndrome (1); cleidocranial dysplasia (1); collagen vascular disease (1); congenital muscular dystrophy (1); dementia (1); Duchenne muscular dystrophy (1); focal segmental glomerulosclerosis (1); insulinoma (1); knee osteoarthritis (1); Marfan syndrome (1); multiple lipomatosis (1); myocardial inflammation (1); myopathy (1); Nestor-Guillermo progeria syndrome (1); pycnodysostosis (1); renal failure (1); tendinitis (1); tumor (1); type 2 diabetes (1); type 2 familial partial lipodystrophy (1); Yunis-Varon syndrome (1).